BARHL2 (BarH like homeobox 2)
Description:
Potential regulator of neural basic helix-loop-helix genes.
Tractability: No criterion of Open Targets' tractability assessment is met for any kind of drug.
Gene: Protein-coding gene on chromosome 1 (90,711,539 to 90,717,302, reverse strand). Ensembl gene ENSG00000143032.
Subcellular location: Nucleus
Gene Ontology:
Molecular function: protein binding; sequence-specific double-stranded DNA binding; DNA-binding transcription factor activity, RNA polymerase II-specific; RNA polymerase II transcription regulatory region sequence-specific DNA binding; DNA binding; DNA-binding transcription activator activity, RNA polymerase II-specific; DNA-binding transcription factor activity
Biological process: regulation of transcription by RNA polymerase II; nervous system development; positive regulation of transcription by RNA polymerase II; regulation of DNA-templated transcription
Cellular component: chromatin; nucleus
Genetic constraint (gnomAD): Loss-of-function variants: 10 observed, 26.95 expected, observed/expected ratio (o/e) 0.37, 90% interval 0.23 to 0.63. The upper end of that interval is the gene's LOEUF score, 0.63, which puts it in group 2 of 6, group 1 being the genes least tolerant of losing a copy. Missense variants: 483 observed, 540.14 expected, observed/expected ratio (o/e) 0.89, 90% interval 0.83 to 0.96. Synonymous variants: 248 observed, 226.76 expected, observed/expected ratio (o/e) 1.09, 90% interval 0.99 to 1.22.
Homologues: Orthologues: chimpanzee BARHL2 (99% identical), pig BARHL2 (96% identical), rabbit BARHL2 (96% identical), dog BARHL2 (95% identical), guinea pig BARHL2 (95% identical), mouse Barhl2 (93% identical), rat Barhl2 (93% identical), macaque BARHL2 (89% identical), zebrafish barhl2 (79% identical), tropical clawed frog barhl2 (77% identical), Drosophila melanogaster B-H1 (34% identical), Drosophila melanogaster B-H2 (33% identical), and 2 more. Paralogues in human: BARHL1 (52% identical), BARX2 (20% identical), BARX1 (19% identical).
Diseases named in the same sentence as BARHL2 in open-access papers:
BARHL2 is named in the same sentence as 13 diseases in open-access papers, as found by Europe PMC text mining. Sharing a sentence is not in itself a finding about the gene and the disease. The quoted sentences say what the papers report.
gastric cancer (7 papers, 2020 to 2023). A primary or metastatic malignant neoplasm involving the stomach. "They identified elevated levels of methylation in the BARHL2 gene in gastric juice from early gastric cancer patients and gastric cancer cell strains, with a decrease observed in patients diagnosed with regular gastritis or atrophic gastritis." (PMID 37932800, 2023). "Assessing the methylation of BARHL2 in EV DNA derived from gastric fluid could serve as a potential biomarker for monitoring the early stages and progression of gastric cancer." (PMID 37932800, 2023). "It is important to mention that BARHL2 has been found aberrantly methylated in epithelial and hematological tumours as well as brain tumours and its putative role as tumour suppressor has been suggested in gastric cancer." (PMID 37301955, 2023). "Moreover, DNA methylation of BARHL2 in exosomal DNA from gastric juice has been recognized as a predictive biomarker of gastric cancer." (PMID 34992636, 2021). "Briefly after that, the group proposed that BARHL2 methylation in gastric-juice derived exoDNA could be useful for early diagnosis of gastric cancer, which yields an area under the curve (AUC) of 0.923 with 90% sensitivity and 100% specificity." (PMID 33297544, 2020). "The researchers used gastric juice samples for the quantification of EV-associated BarH, such as homeobox 2 (BARHL2) DNA methylation, which discriminated gastric cancer (GC) patients from non-GC controls with 90% sensitivity and 100% specificity." (PMID 36831648, 2023).
lung carcinoma (3 papers, 2014 to 2023). "BARHL2, a homebox gene, was found to be methylated in lung cancer or astrocytomas." (PMID 25261372, 2014). "Similarly to BARHL2, OTX2 has been found aberrantly methylated in epithelial tumours including breast and lung cancer." (PMID 37301955, 2023). "BARHL2, DMRTA2, OTX1 and OTX2 were identified as DNA methylation markers for lung cancer." (PMID 35313869, 2022).
meningioma (1 paper, 2013). A generally slow growing tumor attached to the dura mater. "For the malignant meningiomas in our study, 26 genes were identified as significantly hypermethylated at promoter CpG islands, including eight genes involved in the biological pathway of neurogenesis (BARHL2, TLX3, FOXR1, HOXA11, HOXA6, HOXA9, OTX2 and PAX3)." (PMID 23349797, 2013).
rectal cancer (1 paper, 2014). A primary or metastatic malignant neoplasm that affects the rectum. "Notably, many of these genes (ADRA1A, BARHL2, ERAS, ESRRG, RNF220 and ST6GALNAC5) are also targets of the Polycomb Repressor Complex-2, further supporting an important role of epigenetic crosstalk in controlling rectal cancer therapeutic responsiveness." (PMID 25261372, 2014).
tumor (4 papers, 2010 to 2023). "The expression of Human BarH-like homeobox 2 (Barx2), a tumor suppressor linked to the Wnt/β-catenin signaling pathway, was relatively lower in tumor samples than in adjacent samples in NSCLC patients, and low Barx2 expression is associated with poor prognosis." (PMID 36532721, 2022). "In this investigation, we attempted to explore whether BarH-like homeobox 2 (BARX2), a well-known tumor suppressor, had anti-cancer properties on NPC, and the possible mechanisms." (PMID 35037835, 2022).
BARHL2 also shares sentences with these, for which no sentence is quoted: cancer (3 papers); astrocytomas (1); brain tumours (1); esophageal squamous cell carcinoma (1); gastritis (1); gastrointestinal tumours (1); glioma (1); nasopharyngeal carcinoma (1).